CD79B (CD79b molecule)
Diseases named in the same sentence as CD79B in open-access papers (continued):
Sharing a sentence is not in itself a finding about the gene and the disease.
pancreatic cancer (1 paper, 2023). "The activity of pancreatic cancer cells was also significantly reduced after CD79B knockdown in A549 and H1299 cell lines (***P<0.001, **P<0.001)." (PMID 37622116, 2023).
pulpitis (1 paper, 2023). Inflammation of the dental pulp. "The abundance of various immune cells was significantly abnormal in pulpitis tissues, among which the expression of eight lncRNAs was significantly correlated with the expression of B cell marker protein CD79B." (PMID 37238161, 2023). "In pulpitis, we also found immune-related lncRNAs that could bind to CD79B and regulate B cell infiltration." (PMID 37238161, 2023).
Richter syndrome (1 paper, 2024). Transformation of chronic lymphocytic leukemia into aggressive non-Hodgkin's lymphoma, usually diffuse large B-cell lymphoma (immunoblastic or centroblastic variant). "Conversely, high CD79b expression predicts an unfavorable outcome in CLL and can also suggest potential complications such as Richter syndrome, explaining the high white cell count and eosinophils count encountered in these patients." (PMID 39329950, 2024).
seminoma (1 paper, 2023). A radiosensitive malignant germ cell tumor found in the testis (especially undescended), and extragonadal sites (anterior mediastinum and pineal gland). "To further examine the functions of MMP9 and CTSK in seminoma, we subset immune cells (PTPRC+), and explored the expression patterns of markers for T cells (CD3D+ and CD3E+) and B cells (CD79B+; MS4A1+ and SDC1+)." (PMID 38123589, 2023).
Waldenström's Macroglobulinemia (1 paper, 2024). "Despite recurrent and activating mutations, including MYD88, CXCR4, ARID1A, KMT2D, and CD79B were identified, the genetic basis for Waldenström's Macroglobulinemia (WM) and the risk of progression of IgM MGUS to WM remain to be fully elucidated." (PMID 39711167, 2024).
X-linked agammaglobulinemia (1 paper, 2020). X-linked agammaglobulinemia (XLA) is a clinically variable form of isolated agammaglobulinemia, an inherited immunodeficiency disorder (see this term), and is characterized in affected males by recurrent bacterial infections during infancy. "Fourth, genetic mutations of non-X linked agammaglobulinemia encoding for pre-BCR and/or BCR complex (such as IGHM, CD79a, CD79b, and IGLL1 genes) and for activating mTOR signaling (such as PI3KD and PIK3R1 genes)." (PMID 33013854, 2020).
tumor (80 papers, 2008 to 2026). "SELL (a regulator of lymphocyte homing), RAMP2 (implicated in vascular remodeling), and CD79B (a B cell receptor component) exhibited tumor-specific upregulation and functional roles in GC proliferation, as validated by siRNA knockdown." (PMID 40547199, 2025). "To investigate the functional roles of SELL, RAMP2, and CD79B in GC progression, we performed siRNA-mediated knockdown of these genes in GC cell lines and assessed their impacts on tumor-associated pathways via qPCR." (PMID 40547199, 2025). "Mutations in the MYD88 and CD79B genes, which play crucial roles in the tumor’s biological framework, are linked to immune privilege and tumor immune evasion." (PMID 40299829, 2025). "MYD88 L265P and CD79B Y196 mutations were detected in 9/14 (64%) and 2/13 (15%) tumor biopsies, respectively." (PMID 38566053, 2024). "Yet, the staining for CD79B was low in the tumor carrying KLHL6E547K mutation." (PMID 38630892, 2024). "Moreover, MYD88 and CD79B were identified as cancer driver genes in the high-risk group, which is in good agreement with the previous findings that MYD88 and CD79B mutations have been associated with tumor response and survival in DLBCL patients." (PMID 34745101, 2021). "In CC tissues, CD79B expression was associated with infiltration of multiple immune cells, such asB cells, T cells, and macrophages, suggesting it may play a role in regulating the tumor immune microenvironment." (PMID 36406115, 2022). "One possible mechanism of MYD88/CD79B-derived lymphomagenesis involves TLR/MYD88 signaling, which might initiate tumor growth in IP sites, characterized by their favorable microenvironments, whereas concomitant CD79B mutations could further promote lymphomagenesis by enhancing the BCR signaling." (PMID 33050534, 2020). "MYD88 (73%) was the most common mutation in primary tumor tissues, followed by the mutation of PIM1(64%) and CD79B (55%)." (PMID 40475774, 2025). "PPI network analysis identified SELL, CD79B, and RAMP2 as hub genes, all significantly linked to survival and differentially expressed across tumor grades/stages." (PMID 40547199, 2025). "Polatuzumab vedotin, an antibody-drug conjugate targeting CD79b, delivers cytotoxic drugs directly to tumor cells." (PMID 41293167, 2025). "Studies have shown that anti-CD79b immunoconjugates with potent payloads like MMAF or DM-1 induce sustained tumor regression or complete remission in preclinical models, whereas ADCs targeting CD79a often result in tumor relapse." (PMID 39770542, 2024). "In our study, we detected 1,993 cells with CD79A and CD79B expressions, consisting of 1,305 cells from the control samples and 688 cells from the tumor samples." (PMID 38386050, 2024). "Other tumor-derived membrane proteins, including CD19 and CD79b, have been identified on neutrophils following co-incubation with tumor cells." (PMID 38474175, 2024). "Three representative markers, CD20, CD79A and CD79B, were used to test the accuracy of the tumor cell population." (PMID 37120690, 2023). "Tumor cells were robustly immunoreactive to CD-20 and CD-79b, corroborating their B-cell phenotype (respectively)." (PMID 36992464, 2023). "An antibody-drug conjugate that is internalised by CD79B+ tumour cells, delivering conjugated monomethyl auristatin E, which prevents tubulin polymerization, and results in cell cycle arrest and apoptosis." (PMID 37681023, 2023). "CGP of PCL tissues revealed the tumor to be wildtype for CD79B, MYD88, CARD11, and TNFAIP3, with genomic alterations detected in SMO, CIITA, ETS1, HST1H1D, and SOCS1." (PMID 36342081, 2023). "The most frequently mutated genes in the tumor tissue cohort were DTX1 (37%), CD79B (35%), BTG1 (30%), BTG2 (30%), and TMSB4X (30%)." (PMID 36280874, 2022). "It has also been reported that CD79B was differentially expressed in tumor tissues; for example, CD79B expression was found to be low inB cell chronic lymphocytic leukemia (B-CLL)." (PMID 36406115, 2022).
tumor (continued). "While in our cohort, CD79B was correlated with higher IL-10 level in the vitreous (P=0.030, 1-β=0.740), which indicated higher tumor load in the vitreous cavity." (PMID 35928872, 2022). "This is the first study to report that a high level of CD79 B expression is related to better prognosis, which indicates that high CD79B expression is necessary for efficacious anti-tumor responses." (PMID 36406115, 2022). "In this sense, genotyping of ctDNA by CAPP-Seq allows the recovery of 100% of the tumor-confirmed actionable mutations of DLBCL, such as EZH2, MYD88, and CD79B." (PMID 36230571, 2022). "The analysis of the GEPIA2 data showed that the expression of CD79B mRNA in tumor tissues was significantly lower than that in normal cervical tissue (p < 0.05)." (PMID 36406115, 2022). "They found that the expression of CD79b on tumor cells of patients with different types of B-cell malignancies was wide." (PMID 34256851, 2021). "CD79B mutations were shown to cause chronic activation of BCR signaling and constitutive NF-κB activation, further promoting tumor cell growth within the immunosuppressive TME." (PMID 34745101, 2021). "CD79b is exclusively expressed in immature and mature B cells and is overexpressed in ≥80% of neoplasms." (PMID 34358100, 2021). "It would be of interest to compare the profiles of lymphocyte phenotypes, clonality and determine the presence of recurrent mutations (involving MYD88, CD79B and PIM1 genes) in the tumor, plasma and bone marrow." (PMID 28636991, 2017). "Tumor characteristics were assessed using immunohistochemical staining for CD79B, LC3, and TERT." (PMID 42113085, 2026). "By eliminating CD79b-expressing B-cells, PolaV may reduce tumor-induced immune suppression and enhance tumor antigen presentation to immune cells." (PMID 40299416, 2025). "In DLBCL, somatic mutations in genes such as CD79A, CD79B, and CARD11 drive ligand-independent persistent activation of BCR signaling, thereby providing sustained proliferative and survival signals that promote tumor progression." (PMID 41142795, 2025). "Additionally, we compared the distribution of B cells (based on CD79A and CD79B expressions) between the control and tumor groups." (PMID 38386050, 2024). "In our cohort, only one adult tumor showed both MYD88 and CD79B mutations." (PMID 38730692, 2024). "The results showed that in the tumor microenvironment created by M2 macrophages, the expression of CD79B in tumor cells was down-regulated, which may lead to abnormal BCR signaling." (PMID 35397536, 2022). "We also found that CD79B expression was positively correlated with Treg infiltration levels, which may indicate that they can suppress the anti-tumor immune response." (PMID 36406115, 2022). "Although the number of infiltrating cytotoxic CD8+ T cells is increased in CC samples with high levels of CD79B expression, their anti-tumor function may be limited to some degree due to the increased Treg infiltration." (PMID 36406115, 2022). "The downregulation of CD79B in the tumor immune microenvironment may lead to abnormal BCR signaling, affecting B cell activity and leading to immunosuppression." (PMID 35397536, 2022). "Only the anti-CD79b ADCs were found to regress tumor volumes." (PMID 34358100, 2021). "To validate whether recurrent AITL mutations are tumor‐specific, we performed flow sorting for 10 AITL including neoplastic‐cells (CD3+/PD1+), myeloid (CD68+/CD11B+), and B‐cells (CD3‐/CD79B+) and WES was performed on the tumor enriched cell fraction for nine AITLs." (PMID 40510016, 2025). "Notably, the HBsAg-positive group exhibited a decreased mutation frequency of CD79B, a key molecule of the BCR pathway; thus, HBV infection may affect the immune escape mechanism of tumor cells and, thus, the mutational selection of CD79B." (PMID 38318173, 2024).
tumor (continued). "Further work is needed to confirm antigen presentation function among CD79b+ neutrophils, to understand how the B cell program regulates antigen presentation phenotypes in neutrophils, and whether this function in CD79b+ neutrophils impacts tumor progression." (PMID 38022639, 2023). "Other studies also reported that CD79A and CD79B mutations modify distal BCR signaling in collaboration with other mutations of the BCR signaling network via modulation of NF-κB signaling (with an effect on survival, apoptosis, and proliferation of tumor cells)." (PMID 38203179, 2023). "Thus, by blocking BCR internalization and by enhancing BCR signaling, CD79B mutations may prevent induction of anergy, which in the case of CLL may be primarily overcome by co-stimulatory signals from the tumor microenvironment." (PMID 32481736, 2020). "All neoplasms labeled positively for MUM-1, negatively for PAX5, and were variably CD20- and CD79b-positive." (PMID 40215400, 2025). "In analyzing B cells in the tumor microenvironment, B cells were separated into two clusters: one termed as follicular B cell, with high expressions of MS4A1, CD79B, CD52, and another termed as plasma cell, with high expressions of IGHG1, IGHG4 and MZB1." (PMID 38443340, 2024). "Compared to normal tissues, significantly higher expression for SKAP1, LAT and lower expression for CD1D, CD79B, CETP, PTGDS was found in tumor tissues in the TCGA-BRCA cohort." (PMID 37598257, 2023). "CD79B was highly expressed in B cells, while PEBP1 was highly expressed in various types of cells in the tumor microenvironment." (PMID 37622116, 2023). "Meanwhile, immunohistochemical staining of the tumor tissue of another 65-year-old female patient with LUAD showed some degree of protein expression of both CCL17 and CD79B (naive B cells marker molecule)." (PMID 35321241, 2022). "However, in barrier-protected tissues where tumor cells experience less antigenic stimulation, NF-κB pathway activation is particularly dependent on chronic B-cell receptor signaling and Toll-like receptor signaling maintained by CARD11, CD79B, and MYD88 mutations." (PMID 33747936, 2021). "Therefore, the anti-tumor effects of scFv-OA2-siRAPSYN were definitively confirmed in the cell line-based mouse model, and the advantage of anti-CD79B-scFv conjugation was verified in vivo." (PMID 38741123, 2024). "In addition, ALOX15B, LCN2, PRSS12, CD79B and ITSN2 showed tumor lesion-specific changes for all four patients." (PMID 37488117, 2023). "The results showed that CCL17 and CD3G (CD4/CD8+ T cell marker molecule), CD4 (CD4+ T cell marker molecule), and CD79B (naive B-cell marker molecule) were expressed to some extent in tumor tissues of three LUAD patients without dysregulation." (PMID 35321241, 2022). "Additional evidence for a potential role of the BCR pathway in the pathogenesis of MCL was provided by phospho-proteomic analysis of MCL cell lines and primary tumor samples demonstrating constitutive activation of multiple BCR signaling molecules, including CD79B, LYN, SYK, BLNK, BTK, and PLCγ2." (PMID 32481736, 2020). "BL is composed of monomorphic B-cells with basophilic cytoplasm and numerous mitotic figures that express B-cell antigens such as IgM, CD19, CD20, CD22, and CD79b, germinal center markers such as CD10 and BCL-6, and the proliferation marker Ki-67 in nearly all tumor cells." (PMID 27818811, 2016). "As a control for siRNA sequence, we used anti-TENB2-siPPIBmm and, as a control for antibody targeting of the tumor cells, we used anti-CD79b-siPPIB (these tumor cells do not express CD79b)." (PMID 25550431, 2015). "Sequencing of tumor tissues from 22 patients showed that MYD88 mutations were the most frequent genetic alterations, two patients with CARD11 mutation did not respond to treatment and three patients without an MYD88 or CD79B had response after treatment." (PMID 40475774, 2025).
tumor (continued). "Notably, scFv-OA2-siRAPSYN treatments resulted in more potent anti-tumor effects than the siRNA without scFv region, further confirming the critical roles of anti-CD79B-scFv for specific targeting and subsequent gene silencing." (PMID 38741123, 2024). "Various genes that were significantly changed, such as CD79B, CLDN2, SPP1 and IGHG3 were the marker genes of the identified cell types or sub-populations, probably owing to the high heterogeneity in cellular compositions across the tumor samples, as observed above." (PMID 37488117, 2023). "Importantly, we did not detect the control anti-CD79b ARC in or near the tumor, indicating that the localization of the anti-TENB2 ARC components depended on the proper antibody–antigen interaction." (PMID 25550431, 2015). "RC cells had the following immunophenotype: positive for CD10, CD19, CD20, CD22, CD38, CD43, CD44, and CD79b and negative for CD3, CD4, CD5, CD8, CD11c, CD14, CD30, CD56, and CD200, which was identical to the primary tumor cells." (PMID 26515759, 2015).
cancer (31 papers, 2012 to 2025). A tumor composed of atypical neoplastic, often pleomorphic cells that invade other tissues. "The current study compared the gene expression of 770 cancer-associated genes between a CD79B-mutated and a CD79B wild type primary, treatment-naïve DLBCL population." (PMID 41295250, 2025). "The main objective of the current study was the comparison of gene expression of 770 cancer-associated genes in 48 primary, treatment-naïve DLBCLs according to their CD79B mutational status." (PMID 41295250, 2025). "The expression levels of the CD79B gene were associated with prognosis in various cancers." (PMID 37671167, 2023). "An antibody-drug combination (ADC) called polatuzumab vedotin limits harm to healthy cells by directly delivering a strong cytotoxic chemical to cancer cells that express CD79B." (PMID 40725080, 2025). "A hypoxia-mediated activation leading to cancer progression was reported for WNT11, the second most up-regulated gene in the CD79B-mutated group." (PMID 41295250, 2025). "STAT3 is a transcription factor, which is frequently constitutively activated in cancer as in ABC DLBCLs, involved in many central oncogenic processes and its gene was also up-regulated in the CD79B-mutated group." (PMID 41295250, 2025). "Initially, we planned to test our approach with three crucial genes–PAX5, MYC, and CD79B –- known to play pivotal roles in cancer development and DLBCL growth." (PMID 39469218, 2024). "Further work will define the CD79b+ neutrophil’s role in cancer progression and determine its usefulness as a biomarker and therapeutic target." (PMID 38022639, 2023). "Here we described the novel expression of CD79b among human neutrophils and show that these cells are restricted to the bone marrow during steady-state but appear in the periphery during cancer." (PMID 38022639, 2023). "As shown in the Oncodrive plot, MYD88, CD79B, KHL6, and MUC4 were identified as cancer driver genes in the high-risk group whereas only PEG3 and ZNF337 were identified in the low-risk group." (PMID 34745101, 2021). "Additional RNA ISH for cxcr4a, another gene up-regulated in hMYC pre-B vs. T-ALL, showed identical staining to cd79b and opposite staining to lat in two different specimens, demonstrating hMYC+/cd79b+/cxcr4a+/lat- cells correspond to B-lineage GFPlo cancers." (PMID 30111845, 2019). "Cluster of differentiation (CD) markers such as CD79b, CD45, CD23, CD22 and CD81 serve as reliable prognostic indicators in CLL as well as the human leukocyte antigen (HLA) with its well-documented associations with various cancers." (PMID 39329950, 2024). "Polatuzumab vedotin, marketed under the trade name POLIVY®, is a CD79b-targeted antibody-drug conjugate that preferentially delivers a potent anti-mitotic agent (monomethyl auristatin E) to B cells, resulting in anti-cancer activity against B-cell malignancies." (PMID 37063860, 2023). "YKL-40 gene expression was primarily increased in the fibroblast (gene annotation: COL1A, BGN, DCN), myeloid (gene annotation: CD68, LYZ, AIF1), cancer (gene annotation: EPCAM, KRT7, KRT18), and B-cell (gene annotation: CD79A, CD79B) populations in cancer tissue compared to healthy tissue." (PMID 35631632, 2022). "Moreover, four cancer-associated genes showed a high frequency of copy number gain in both datasets (i.e. TERT, FCGR2B, CD79B and PRKAR1A)." (PMID 29371938, 2017). "Other candidates, such as CD79B, MAP4K1, GRAP, TNFRSF13C, and INA, had comparable scores and are candidates for further study, as they have also been implicated in carcinogenesis of other cancer types." (PMID 28146432, 2017). "Disruption of CD79B and MYC showed a notably higher impact on cancer cell survival, diminishing the cell viability up to 42% and 22%, respectively." (PMID 39469218, 2024).